FAP (fibroblast activation protein alpha)
Diseases named in the same sentence as FAP in open-access papers (continued):
Sharing a sentence is not in itself a finding about the gene and the disease.
tumor (continued). "FAP, also found abundant in CAFs, was recently shown to mediate immunosuppression in a transplanted murine tumour model, while the release of the DAMP, high-mobility group protein B1 (HMGB1), plays a key role in sustained inflammatory signalling." (PMID 36293328, 2022). "Within tumours, FAP promotes tumour growth by promoting angiogenesis and ECM remodelling and facilitates the progression of tumours by supressing the anti-cancer immune response." (PMID 35359378, 2022). "QUESTION: Do albumin binder–conjugated FAPI radiopharmaceuticals have high FAP specificity and provide enhanced tumor retention and improved radiotherapy efficiency?" (PMID 34593598, 2022). "The combinational use of FAP-DNA vaccine and other tumor antigen-specific DNA vaccines showed synergic effects of anti-tumor immunity characterized by increased CD8+ T cell infiltration and decreased macrophage infiltration." (PMID 36324128, 2022). "FAP plays a pivotal role in tumor microenvironment, including reduced levels of anti-angiogenic factors, elevated levels of transforming growth factor β, and affected matrix processing enzymes." (PMID 35113192, 2022). "IHC analyses showed the presence of active YAP1 in tumor cells and stromal fibroblasts and demonstrated FAPα immunoreactivity exclusively in stromal fibroblasts." (PMID 35986369, 2022). "Fibroblast activation protein alpha (FAP) is a type II integral membrane protein belonging to the dipeptidyl peptidase 4 protein family and is famous for its high expression in tumor stroma." (PMID 35405864, 2022). "Upon cleavage by FAP, the nontoxic prodrug is activated to a potent toxin that kills both FAP+ and neighbouring FAP− cells in the tumour." (PMID 35158891, 2022). "The highly tumor restricted distribution and specific proteolytic activity of FAPα make it a very attractive target for precision cancer diagnosis and treatment." (PMID 35664057, 2022). "Treating the FAP+ CAF-depleted mice with ICIs targeting PD-L1/CTLA-4 dramatically reduced tumor volumes." (PMID 36627901, 2022). "In particular, FAP expression in tumor cells was an independent prognostic factor and independent predictive factor for recurrence." (PMID 35818720, 2022). "Together, these results indicate that [68Ga]Ga-DOTA-Siglec-9 can detect increased tumor uptake of FAP-IL2v." (PMID 35874707, 2022). "In summary, our results show clear FAP expression in primary tumor tissue, thus showing the suitability of our syngeneic tumor model to test a combinatorial treatment with DB and the immunocytokine FAP-IL-2v." (PMID 36230765, 2022). "Targeting FAP is not limited to tumor cells but can also be applied to the CAFs in the stroma that support tumor development and maintenance." (PMID 35608703, 2022). "Tumor-to-muscle uptake of [68Ga]Ga-DOTA-Siglec-9 was significantly higher in the FAP-IL2v-treated group than in the vehicle-treated group 7 days after baseline imaging, and this was confirmed by tumor autoradiography analysis." (PMID 35874707, 2022). "Plasmid cDNA encoding FAP has successfully provoked cellular immune response to FAP and benefit to the host in reducing tumor burden." (PMID 35252279, 2022). "We used a different approach of simultaneously implanting individual animals with a FAP-negative and a genetically altered FAP-expressing and otherwise identical tumor line." (PMID 34957527, 2022). "Six diagnostic genes were mutated in descending frequency in the tumor group: COL4A1, ABCA8, MAMDC2, FAP, TMEM100, and LY6E." (PMID 36685898, 2022). "In preclinical and clinical trials, FAP-targeting molecular imaging radiotracers have shown promising results with respect to tumor diagnosis." (PMID 36263225, 2022). "Similar to PT-100, another amino boronic dipeptide inhibitor of FAP activity, PT-630 (GluBoroPro dipeptide), demonstrated retardation of tumour growth in preclinical animal models." (PMID 35814453, 2022).
tumor (continued). "Post-CD10 and post-FAP were related to tumor size (p=0.006, p=0.002, respectively), ypT (p=0.047, p<0.001, respectively), and ypN (p=0.034, p=0.034, respectively)." (PMID 36387219, 2022). "FAP and integrin αvβ3 are two highly expressed targets in tumor stroma and angiogenic endothelial cells." (PMID 36276644, 2022). "In the face of such potential systemic toxicity concerns, nanoparticle-aided targeted delivery of FAP targeting therapies are currently being explored to minimize toxicity and improve tumour specificity." (PMID 35814453, 2022). "Longitudinal [68Ga]Ga-DOTA-Siglec-9 PET/CT imaging revealed a relatively equal tumor-to-muscle uptake in the FAP-IL2v-treated and vehicle-treated groups 3 days and 5 days after baseline imaging." (PMID 35874707, 2022). "In fact, co-targeting FAP in combination with tumor-centric FAP-targeting strategies was shown to be more effective." (PMID 35326670, 2022). "In our study, both FAP expression in tumor cells and FAP expression in CAFs were strongly correlated with PD‐L1 expression." (PMID 35818720, 2022). "Due to their potential as pan-tumor imaging and treatment agents, FAP-targeted radiopharmaceuticals have gained interest in recent years." (PMID 35681588, 2022). "For FAP and PDGFRα, weak staining was observed in the fibromuscular stroma compared to the positively stained regions in the tumor epithelium." (PMID 35530322, 2022). "The result showed that there were the co-existences of VCAN and FAP in the tumor, which was consistent with the analysis result at mRNA level." (PMID 36203562, 2022). "Wnt2 neutralizing antibodies seem to recall the immune response to the tumor through the activation of dendritic cells and FAP-targeted chimeric antigen receptor T cells, leading to depletion of FAP + CAFs, revoking the pro-angiogenic CAFs-related effect." (PMID 36139552, 2022). "FAP-targeted therapy with NIR-PIT can specifically target FAP in the tumor microenvironment and is expected to have a high antitumor effect with less systemic toxicity." (PMID 36418422, 2022). "Fibroblast activation protein (FAP) is a membrane-bound protease that has limited expression in normal adult tissues but is highly expressed in the tumor microenvironment of many solid cancers." (PMID 35608703, 2022). "In tumour tissue, however, approximately three-quarters of all stromal cells (76%) expressed detectable levels of FAP mRNA." (PMID 35296803, 2022). "The anti-tumor activity of anti-FAP CAR-T cells includes inhibiting stromagenesis, thus reducing tumor growth by both immune-dependent and immune-independent mechanisms." (PMID 35326556, 2022). "The dosimetric results and findings described in the T/B ratios of the tumors suggest that [99mTc]Tc-iFAP imaging is a safe and potentially useful tool to assess FAP expression in the tumor microenvironment." (PMID 35631416, 2022). "The R package for immune and stromal scoring of individual tumor samples revealed that FAP expression was positively correlated with immune score as well as stromal score." (PMID 35359436, 2022). "Next, we assessed FAP expression by primary and well-known NB cells, as well as in a murine NB tumor tissue." (PMID 36230765, 2022). "HEK-FAP xenografts were monitored for regrowth out to the end of the study (day 42), with 3 and 9 tumor-free (< 10 mm3) mice out of 10 in the 30 and 60 MBq 177Lu-FAP-2286 treatment groups, respectively." (PMID 35608703, 2022). "A better correlation between FAPI uptake and FAP expression was observed in tumor surgical specimens than in surgical plus biopsy specimens, just as surgical specimens can show the true expression of FAP in tumors better than puncture specimens." (PMID 34870727, 2022). "In this scenario, the tumor model Sarc4809 would be representative of cancers of mesenchymal origin, where FAP is present on tumor cells contributing to their histologies and tumorigenesis and 177Lu-FAP-2286 would render cytotoxic radiation to tumor cells." (PMID 35608703, 2022).
tumor (continued). "FAP is an excellent target for tumour stroma, and 68Ga-FAPIs, as newer imaging tracers, present a promising alternative to [18F]F-FDG." (PMID 36698416, 2022). "FAP overexpression facilitates tumor progression and invasion by manipulating extracellular matrix remodeling, angiogenesis, intracellular signaling, epithelial-to-mesenchymal transition (EMT), and immunosuppression." (PMID 35359436, 2022). "FAPα, as a marker for CAFs, has been known to play a role in cancer growth, invasion, and metastasis by degrading the tumor microenvironment extracellular matrix and inducing epithelial-mesenchymal transition 61-64." (PMID 34976180, 2022). "Studies have indicated that the production of chemokine (C-X-C motif) ligand 12 (CXCL12) by FAP+ CAFs within the cancer cell-rich region of a tumor impedes T cell infiltration leading to immunosuppression." (PMID 36263225, 2022). "The authors anticipated that a cyclic peptide targeting FAP would have an improved tumor retention time over the small molecule-based radiopharmaceuticals." (PMID 36182995, 2022). "In contrast, the combinatorial immunotherapy with DB and FAP-IL-2v resulted in superior antitumor effects, showing the strongest tumor growth inhibition compared to every control group." (PMID 36230765, 2022). "FAP expression has been reported on the surface of tumor stromal cells, macrophages, and tumor cells." (PMID 34870727, 2022). "In particular, adoptive transfer of FAP-CAR T-cells reduces tumor growth in a FAP-dependent fashion and can be combined with Ad.E7 antitumor vaccine." (PMID 36569859, 2022). "A key advantage of this concept is that apart from binding to IL-2R expressed on immune effector cells, binding to FAP allows for the retention of IL-2v in the tumour, which can further affect immune cells in the TME." (PMID 35814453, 2022). "Similar to Casp3, FAPα is highly expressed in the tumor microenvironment, with higher proteolytic activity in a broad range of tumor types." (PMID 35910747, 2022). "The depletion of FAP+CD45+ cells or administration of the HO-1 inhibitor Sn mesoporphyrin has been shown to promote the immune-dependent arrest of subcutaneous tumor growth." (PMID 36263225, 2022). "Depletion of FAP+ CAFs, which exhibited upregulation of proinflammatory factors similar to iCAFs, can decrease tumor volumes in a CD4+ T cell- and CD8+ T cell-dependent manner in a KPC mice model." (PMID 36627901, 2022). "In this regard, FAPα inhibitors have shown promising preclinical results in reducing tumour progression and promoting an antitumour immune response." (PMID 36555218, 2022). "Based on combinations of FAP expression in tumor cells and CAFs, patients with LowT/LowCAFs had better OS and RFS than did those in the other subgroups." (PMID 35818720, 2022). "An orally administered anti-FAP DNA vaccine notably suppressed neoangiogenesis, tumor growth, and the metastasis of orthotopically injected breast carcinoma cells." (PMID 36010899, 2022). "The aFAP-PE38 immunotoxin targeting FAP specifically depletes FAP-positive CAFs to inhibit angiogenesis and induce apoptosis, thereby reducing tumor growth." (PMID 35884382, 2022). "One example is CAR-T cells constructed against the fibroblast activation protein (FAP) to target cancer-associated fibroblasts (CAPs), which secrete growth factors to the extracellular matrix (ECM) to support tumor growth." (PMID 35326556, 2022). "CAR-T therapy targeted against FAP+ cells was shown to delay tumor growth and improve survival, and induce a modest reduction in chemoresistance." (PMID 35892828, 2022). "In vitro and in vivo studies indicated high radiotracer stability in human serum (>95% at 24 h), specific recognition for FAP, high tumor uptake (7.05 ± 1.13% ID/g at 30 min) and fast kidney elimination." (PMID 35011496, 2022). "Genetic or pharmacological depletion of FAP-expressing CAFs reduces tumor growth in preclinical cancer models." (PMID 35884382, 2022).
tumor (continued). "According to the National Cancer Institute Clinical Proteomic Tumor Analysis Consortium (CPTAC) dataset, FAP protein expression is significantly higher in primary PAAD tumor tissues than in normal tissues." (PMID 36263225, 2022). "The first results of [177Lu]Lu-FAP-2286 treatment in a group of metastatic cancer patients demonstrated high tumor uptake and reasonable retention, with stable disease in 2/11 patients after one treatment cycle." (PMID 35788730, 2022). "CAFs represent the most abundant cell type of the BC microenvironment and, consequently, FAP is an excellent candidate as an indirect tumor cell target." (PMID 35327325, 2022). "For better tumor targeting, the IL2v moiety is fused to a fibroblast activation protein (FAP)-specific antibody to selectively promote IL2v immune responses within the tumor microenvironment." (PMID 35874707, 2022). "Specifically, the tumor epithelium (EpCAM), stromal compartment (FAP), immune cells (CD45) and proliferation (Ki67) were analyzed in baseline and 48 h after culturing (representative images from two cases are displayed)." (PMID 36097280, 2022). "We demonstrated a clear correlation between larger tumor volume and higher tracer uptake, which supports the observed pharmacodynamic effects of FAP-IL2v therapy." (PMID 35874707, 2022). "Although the myofibroblasts in CMS1 and CMS4 expressed comparable levels of FAP, single-cell data cannot be used to infer total tumour levels of FAP expression, and hence the ability of FAP expression to discriminate between CMS1 and CMS4." (PMID 35296803, 2022). "Together, our results show an FAP-IL-2v-dependent improvement in the DB-mediated antitumor effects against resistant NB, resulting in delayed tumor growth and an increase in survival compared to the respective monotherapy." (PMID 36230765, 2022). "Differential gene expression analysis of FAP-positive and FAP-negative tumour cells in patient SMC20 identified 388 genes that were significantly upregulated in FAP-expressing tumour cells." (PMID 35296803, 2022). "The depletion of FAP-positive CAFs enhanced anti-tumor immunity, as reported in several studies, proving the validity of the target." (PMID 35326670, 2022). "constructed exosome-like nanovesicles (eNVs-FAP) from fibroblast activation protein-α (FAP) gene-engineered tumor cells." (PMID 35574366, 2022). "Among them, FAP is a type 2 membrane-bound glycoprotein, which belongs to the serine protease family and has been identified as a marker of reactive tumor stromal fibroblasts." (PMID 36104825, 2022). "Others found that FAP stimulates tumour cell invasion and metastasis in a tumour cell-intrinsic manner." (PMID 35296803, 2022). "Fibroblast activation protein (FAP) is a serine protease expressed in cancer-associated fibroblasts (CAF) cells that ubiquitously infiltrate tumors and form part of the tumor microenvironment." (PMID 36230500, 2022). "The novel PET-tracer “FAPI” has the potential to visualize even small tumour deposits employing the tumour-specific expression of fibroblast-activating protein (FAP) in malignant cells." (PMID 36010308, 2022). "A greater proportion of patients with high FAP tumor expression had received taxanes prior to biopsy (11/21 or 52%) compared to those with unaltered FAP transcript levels (68/187 or 36%)." (PMID 35052475, 2022). "Treating solid tumors with FAP CAR T cells alone or in combination with tumor specific antigens have been investigated with success in multiple preclinical tumor models." (PMID 35252279, 2022). "The distinct dipeptide substrate hydrolytic activity of FAPα and its restricted expression in the tumor microenvironment make it an ideal target for an enzyme-activated prodrug strategy." (PMID 35951441, 2022). "We have therefore assessed the efficacy of VV-αFAP TCE in MC38WT tumours, which produce a FAP-positive stroma in vivo, with the intention of combining the treatment with VV-αCEA TCE." (PMID 36405739, 2022).
tumor (continued). "The HAP database verified the expression of FAP at the translational level and found that the protein was highly expressed in tumor tissues." (PMID 35186170, 2022). "The HPA database then verified that FAP was highly expressed in tumor tissues following protein translation." (PMID 35186170, 2022). "For example, FAP is considered to be a CAFs-specific expressed protein, and therefore FAP is often used as a target of CAFs for tumor diagnosis and treatment." (PMID 36046791, 2022). "FAP can serve as an independent prognostic biomarker, promoting the deterioration of the tumor and leading to adverse clinical outcomes in STAD." (PMID 35359436, 2022). "Third, siRNA-mediated knockdown of INHBA in the tumor fibroblasts resulted in significant FAP gene downregulation (P < 0.001)." (PMID 34642171, 2022). "CAFs, with high expression of FAP, play a fundamental role in dynamic communication networks within the tumor microenvironment." (PMID 35631416, 2022). "Fibroblast activation protein (FAP)-targeting radiopharmaceutical based on the FAP-specific inhibitor (FAPI) is considered as a potential alternative agent to FDG for tumor-specific imaging." (PMID 36531015, 2022). "FAP is a widely distributed antigen in epithelial tumor cells, expressed in 90% of epithelial tumor tissues and the microenvironment of several tumor types." (PMID 36051919, 2022). "A blockade of tumour growth by anti-FAP CAR-T cells was validated in human lung cancer xenografts and syngeneic murine pancreatic cancers." (PMID 35158891, 2022). "FAP-specific CAR-T cells have depleted tumor stroma and reduced vascular density, both of which promote tumor progression and metastasis." (PMID 35326556, 2022). "FAP-MB-5 displayed favorable blood stability, excellent FAPα-responsiveness and satisfactory tumor-specific imaging capacity." (PMID 35664057, 2022). "The expression of FAP in the tumor tissues of GC patients was also related to most immune cells and was positively correlated, such as regulatory T cells, macrophages M2, and eosinophils." (PMID 36010886, 2022). "Before the treatment, the tumor-to-muscle uptake ratio of [68Ga]Ga-DOTA-Siglec-9 was similar in the FAP-IL2v-treated and vehicle-treated groups." (PMID 35874707, 2022). "Our findings resulted in a higher median tumor GTV-volume in the FAP-scans while showing a favorable tumor-to-background ratio (TBR)." (PMID 35771317, 2022). "This resulted in the high HEK-FAP tumor-to-background contrast in the 177Lu-FAP-2286 SPECT/CT images without treatment-related acute toxicity or body weight loss in the efficacy studies." (PMID 35608703, 2022). "The infiltration of macrophages, neutrophils, and dendritic cells are positively correlated with these COL8A1, COL10A1, CTHRC1, and FAP, suggesting the need for exploration of their roles in the tumor microenvironment of GC." (PMID 35910202, 2022). "The depletion of FAP+ cells inhibits tumor growth primarily achieved by augmenting anti-tumor immunity." (PMID 36324128, 2022). "When correcting for tumour size the analysis revealed a significantly higher expression of FAP in peritoneal metastases than in liver metastases (median FAP/EpCAM ratio was 1.7 for PM and 0.5 for CRLM, P value = 7.23e-06)." (PMID 35296803, 2022). "The FAP-α specific tailoring and assembling of M1 differed the tumor from the other tissues, which offered better contrast and biodistribution." (PMID 35058435, 2022). "CXCL12 is known to be produced mainly by fibroblast activation protein (FAP)-expressing CAFs in the tumor microenvironment." (PMID 35884382, 2022). "NEPC and AR signaling scores were assessed in each tumor sample and compared between subgroups with high vs. unaltered FAP transcript levels." (PMID 35052475, 2022). "Comparative PET imaging of HT-1080-FAP and HT-1080 tumor–bearing mice and a blocking study showed the FAP-targeting ability in vivo of these 2 tracers." (PMID 34593598, 2022).